EGFR (epidermal growth factor receptor)
Diseases named in the same sentence as EGFR in open-access papers (continued):
Sharing a sentence is not in itself a finding about the gene and the disease.
tumor (continued). "EGFR-TKIs, which can block EGFR signaling, are the standard treatment for patients with EGFR mutations and also very effective to inhibit proliferation of tumor cells." (PMID 40417000, 2025). "Third, tissue biopsies capture only a snapshot of the tumor, potentially missing subclonal EGFR mutations due to tumor heterogeneity." (PMID 41417019, 2025). "For example, studies on the correlation between radiomic features (e.g., tumor texture, shape) and EGFR mutation status have revealed the potential of imaging features in predicting targeted therapy response." (PMID 41002349, 2025). "Primary resistance occurs in 10 to 30% of cases and is influenced by factors such as the type of EGFR mutation, mutant allele frequency, co-occurring genetic alterations, and the immunosuppressive tumour microenvironment." (PMID 40149368, 2025). "Interactions between follicular helper T cells (CD4 TFH), tissue-resident T cells (CD8 TRM), and B cells mediated by the CXCL13–CXCR5 axis are crucial for anti-tumor immunity in EGFR-mutated non-small cell lung cancer (NSCLC)." (PMID 40406143, 2025). "Plasma ctDNA testing effectively tracked treatment response, detecting emerging RAS mutations linked to anti-EGFR resistance and eliminating the need for repeated invasive tumor biopsies." (PMID 40508077, 2025). "FOXP3 has been implicated in tumor-driven immune tolerance, whereas EGFR is a key oncogenic driver of proliferation and chemoresistance." (PMID 41301890, 2025). "Several trials to date have shown that EGFR-TKI efficacy varies as a function of the subtype of EGFR mutation present in the target tumor, with cases harboring 19del mutations attaining greater benefits from TKI treatment relative to 21L858R cases." (PMID 41239252, 2025). "Liquid biopsy-based monitoring of circulating tumor DNA (ctDNA) allows serial detection of emergent resistance alterations, such as secondary EGFR or ALK mutations and MET amplification, often before radiographic progression." (PMID 41472727, 2025). "In mouse xenograft models harboring EGFR 19del, T790M, and C797S triple mutations, co-treatment with honokiol and osimertinib effectively suppressed tumor progression." (PMID 41019287, 2025). "On the other hand, CD109 overexpression has been reported in some cancers and CD109 expression has been associated with chemoresistance by upregulation of EGFR, and alteration of the tumour microenvironment." (PMID 40227788, 2025). "EGFR signaling, which is dysregulated in more than 70% of OC patients, is associated with high tumor mortality." (PMID 39759123, 2025). "The WSIs containing tiles that Tumor Classifier identified as cancerous were subsequently included in the second classification training set for EGFR mutation Classifier." (PMID 40965349, 2025). "Aberrant EGFR signalling is frequently observed in various malignancies and is often linked to aggressive tumour behaviour and resistance to therapy." (PMID 40906384, 2025). "Epidermal growth factor receptor (EGFR), an essential therapeutic target in the anticancer pathway, is associated with tumor cell proliferation, differentiation, apoptosis, and angiogenesis." (PMID 40672372, 2025). "About 30% of NSCLC tumors have targetable mutations, like EGFR, and 28% of tumors will have a PD-L1 score or tumor mutation burden high enough to warrant immunotherapy; a molecular test prior to therapy assesses eligibility." (PMID 40429725, 2025). "Our single‐cell analysis has elucidated the role of ST6GAL1 in the formation of the CRC TME, highlighting interactions of high ST6GAL1‐expressing tumor cells with B cells, tumor‐associated macrophages, and potential EGFR‐related pathways." (PMID 40847469, 2025).
tumor (continued). "Next, we evaluated the association between CIN and tumor hallmark gene signatures after the development of EGFR-TKI resistance by gene set enrichment analysis." (PMID 40136696, 2025). "Functional studies revealed RKIP overexpression reduces tumor aggressiveness and enhances sensitivity to EGFR‐targeted therapies, while its loss promotes resistance." (PMID 40720248, 2025). "These mutations increase EGFR kinase activity, making tumour cells heavily reliant on EGFR signalling for survival—a phenomenon known as “oncogene addiction”." (PMID 40265416, 2025). "Further, IDH1 R132Q expression led to activation of several pro-tumor pathways, including those associated with EGFR and PI3K signaling reminiscent of lower grade mutant IDH1 tumors that progress to higher grade." (PMID 40188944, 2025). "The mechanisms underlying EGFR-TKI resistance are intricate and multifaceted, encompassing factors such as EGFR mutations, activation of signaling pathways, alterations in the tumor microenvironment, tumor heterogeneity, and histological transformation." (PMID 40003951, 2025). "In this article, we have discussed the molecular events that are linked to tumor progression and rewiring of metabolic pathways in EGFR-mutant NSCLCs." (PMID 40940888, 2025). "Both artificial mixed samples containing 1% of 1 of the 3 EGFR gene mutations and tumor samples were used to evaluate the feasibility of the proposed new method." (PMID 40587690, 2025). "In GBM, the abnormally activated EGFR signaling pathway is associated with a variety of malignant biological behaviors of tumor cells, and the elevation of CASP3 indicates the beginning of apoptosis process." (PMID 40391080, 2025). "In summary, this is the first study to explore distinct allelic effects of ADAM9 SNPs in a Taiwanese population, highlighting their impacts on EGFR mutation frequency and tumor progression in LUAD." (PMID 40429751, 2025). "The multivariate analysis for the 5-year OS identified the tumor size (B = 1.549, p < 0.001) and EGFR status (B = 0.783, p = 0.020) as independent predictors of mortality risk, with larger tumors and the EGFR-positive score increasing the hazard of death." (PMID 40150035, 2025). "CD73 has also been implicated in facilitating tumor progression through various signaling pathways, including the EGFR, MAPK, and PI3K/AKT pathways." (PMID 41188606, 2025). "When deregulated in ESCC, amplified EGFR signalling correlates significantly with tumour invasion, and is independently associated with poorer disease-free and overall survival." (PMID 40615716, 2025). "(2016), who linked these features to aggressive tumor phenotypes and reduced differentiation in EGFR-mutant adenocarcinomas." (PMID 40687424, 2025). "This antibody selectively binds a cryptic epitope exposed exclusively on tumor EGFR (when highly overexpressed or in the EGFRvIII variant), sparing normal tissues that express only wild-type EGFR." (PMID 40918539, 2025). "In NSCLC, exosomal proteins such as EGFR and PD-L1 reflect the tumor’s mutational status and immunosuppressive properties." (PMID 41573685, 2025). "Dysregulated and/or mutated EGFR and c-Met lead to tumor cell survival, proliferation, invasion, migration, and development of drug resistance." (PMID 39995668, 2025). "In general, EGFR mutations are detected in tumor tissue or liquid biopsies/cfDNA by DNA sequencing, but PCR-based approaches for the targeted detection of specific hotspot mutations also exist." (PMID 40075878, 2025). "Increasing evidence has revealed that inflammation plays a crucial role in the tumor biology of EGFR-mutated NSCLC." (PMID 41268168, 2025).
tumor (continued). "The ErbB family is involved in organ growth, including the mammary gland and central nervous system, and EGFR mutations are common in glioblastoma, promoting tumor growth." (PMID 40426980, 2025). "MIG-6-deficient mice exhibit hyperactivation of EGFR signaling and skin hyperplasia, and are highly prone to tumor formation in skin, lung, and other tissues." (PMID 40535815, 2025). "AZD9291 inhibits EGFR signaling, including T790M mutations, while Dox induces DNA damage, leading to enhanced tumor cell apoptosis." (PMID 40733107, 2025). "This review provides new perspectives on EGFR's activation, mutations, and their impact on tumor immunotherapy." (PMID 40859900, 2025). "Afatinib and Gefitinib, as EGFR-targeted therapies, are closely related to EGFR mutations in tumor cells." (PMID 41179292, 2025). "Our study showed that the rs884225 SNP was significantly associated with LUAD susceptibility and EGFR protein expression levels in LUAD tumor tissues." (PMID 40438325, 2025). "Tumor heterogeneity plays a critical role in the development of EGFR-TKI resistance in EGFR-mutated NSCLC." (PMID 40003951, 2025). "This is likely to be a result of the extremely limited quantity of tumor sample examined, which corresponds to the low allele frequency of 8% of the EGFR mutation." (PMID 40768678, 2025). "A Fondation One® test on tumor biopsy was requested in November 2023, which concluded an EGFR mutation and identified CDK6 amplification, HGF amplification, and CDKN2A/B rearrangement." (PMID 40364160, 2025). "Yet, the current study did not assess the influence of CIN-dependent cGAS–STING signaling activity in EGFR-mutated NSCLC on the tumor immune environment or the efficacy of EGFR-TKI therapy." (PMID 40136696, 2025). "Retinoic acid-induced protein 3 was furthermore unique to the GS 6–7 U-EV proteome and can affect EGFR signalling and has also been linked to tumour suppression." (PMID 40725142, 2025). "Targeted therapy was administered to patients whose tumours harboured ALK or EGFR mutations, in accordance with the local reimbursement policy, in 6% of cases." (PMID 40650126, 2025). "This is explained by the strong enrichment for KRAS mutations among NS-LUAD tumours on the SD trajectory, versus the enrichment for EGFR mutations among those on the NSD trajectories." (PMID 41509216, 2025). "Univariate analysis revealed associations between EGFR mutation and gender (P = 0.013), smoking history (P = 0.001), λHU (P = 0.049), and tumor surface area (P = 0.043)." (PMID 41244899, 2025). "EGFR overexpression and activation of its downstream pathways are primary contributors to both mutations in tumor cells and their development of drug resistance." (PMID 39907159, 2025). "Circulating tumor DNA (ctDNA) was analyzed using the Cobas EGFR Mutation Test and compared to tissue-based next-generation sequencing (NGS)." (PMID 39996857, 2025). "Afatinib irreversibly inhibits EGFR and ErbB2 tyrosine kinases, reducing tumor cell proliferation, invasion, and metastasis, particularly in tumors with EGFR/ErbB2 overexpression or mutations." (PMID 40281132, 2025). "EGFR, one of the most prevalent oncogenic mutation sites in cancer cells, is associated with tumor cell proliferation, migration, and evasion of apoptosis." (PMID 40598793, 2025).
tumor (continued). "In the present study, we propose a two‐stage AI‐based approach that exploits CNNs to distinguish between normal tissue and tumor tissue and to subsequently predict the mutational status of EGFR in NSCLCs, particularly for ADCs." (PMID 40965349, 2025). "These mutations enhance EGFR activity, driving tumor cell proliferation, angiogenesis, migration, and invasion, thereby accelerating tumor progression." (PMID 40429751, 2025). "Here, we report the largest EGFR–METex14 co-mutation series to date-seven tumours diagnosed between 2019 and 2024 at three Chinese tertiary hospitals—and compare them with 12 METex14-only and 709 EGFR-only cohorts." (PMID 41316444, 2025). "A disintegrin and metalloprotease 17 (ADAM17), another protein associated with chemoresistance, enhances tumor cell proliferation and survival via the epidermal growth factor receptor (EGFR) pathway by cleaving various ligands such as amphiregulin (AREG)." (PMID 40757000, 2025). "Developing less invasive approaches, particularly proteomic evaluation of circulating tumor cells (CTCs) for EGFR mutation profiling, remains crucial." (PMID 41439947, 2025). "Exosomes, which are directly secreted into bodily fluids by tumor cells, encompass components such as ncRNAs and protein alterations (including EGFR mutations), thereby rendering highly distinctive and representative information." (PMID 40176898, 2025). "Long-term exposure to PM2.5 has been shown to result in persistent EGFR activation, increased cell proliferation, and tumor growth in human adenocarcinoma cells harboring specific EGFR mutations (L858R and T790M)." (PMID 39578555, 2025). "This suggests that magnolol's anti‐tumour activity is associated with the suppression of the EGFR/NF‐κB signalling axis, which plays a critical role in OSCC progression." (PMID 40830825, 2025). "Recent advances in circulating tumor DNA (ctDNA) analysis have provided a noninvasive method for dynamically monitoring the EGFR mutation status, especially the emergence of resistance-related mutations." (PMID 40486879, 2025). "Studies have shown that 40 combined with cetuximab can prevent obvious tumour anti-proliferative response caused by EGFR dimerisation." (PMID 40172117, 2025). "The cellular stress induced by the EGFR-TKIs in EGFR-positive lung tumors triggers the release of tumor-associated antigens." (PMID 41472727, 2025). "These parameters correlate with tumor growth patterns and aggressiveness, potentially linked to EGFR-driven oncogenic pathways." (PMID 41244899, 2025). "These mutations in EGFR are considered to drive oncogenic progression and tumor aggressiveness, and they are, therefore, targeted." (PMID 40649937, 2025). "Other investigators have reported that STING stimulation with STING agonists or irradiation improves the tumor microenvironment and sensitivity to EGFR-TKIs and immune checkpoint inhibitors in EGFR-mutated mouse tumor models." (PMID 40136696, 2025). "Single-cell genomics for common GBM mutations, GFAP staining, tumour specific anomalies like amplification of EGFR gene and gains and losses in chromosomes 7 and 10 genomic regions by chromosomal and array CGH on whole genome amplification." (PMID 40867329, 2025). "As the molecular analysis of the tumor cells showed mutant EGFR, the patient was given Tagrisso (osimertinib), a targeted therapy for EGFR mutation." (PMID 40134856, 2025). "Concordance of detection for clinically important EGFR variants between cfDNA and tumor DNA in stage II cases was 11% (1/9 cases) and 80% in both stage III (4/5) and stage IV (4/5) cases." (PMID 40282516, 2025). "At present, the safety, tolerability, pharmacokinetics, and anti-tumour activity of NCT05394831 in patients with EGFR-mutated advanced NSCLC are being evaluated in phase 2 clinical trials, and the results have not yet been announced." (PMID 40172117, 2025).
tumor (continued). "Experimental validation demonstrated robust tumor-targeted delivery and the potent gene silencing efficacy of the EGFR- and survivin-targeting siRNAs, resulting in a significant reduction in tumor size and the inhibition of tumor-associated vasculature." (PMID 40422200, 2025). "This mutation is associated with persistent activation of the EGFR signaling pathway, resulting in uncontrolled cell proliferation and tumor growth." (PMID 39940838, 2025). "Oligonucleotides designed to detect EGFR mutation status can be applied to patient tumor samples to estimate a possible drug resistance scenario." (PMID 40332084, 2025). "EGFR-TKIs have achieved tumor regression in many EGFR-mutated NSCLC cases; however, all tumors eventually become resistant to EGFR-TKIs through various mechanisms, including secondary EGFR mutations and MET gene amplification." (PMID 40136696, 2025). "Specifically, miR-7, which is highly represented in the brain, is abnormally reduced in GBM, and has been associated with the inhibition of tumor proliferation by blocking epidermal growth factor receptor (EGFR) and PI3K." (PMID 40813676, 2025). "Our results demonstrate the potential of combining biomarkers that represent microenvironmental elements like immune infiltration and angiogenesis as well as tumor-intrinsic (cell-autonomous) changes like EGFR amplification and IDH mutations." (PMID 41311621, 2025). "Meanwhile in NSD tumours, EGFR mutations and copy number gains, in addition to the gains of additional growth factor receptor genes PDGFRB and FGFR4, suggest that this pathway is activated via a different mechanism." (PMID 41509216, 2025). "Circulating tumor DNA (ctDNA) enables dynamic monitoring of RAS mutations during anti-EGFR therapy, capturing on-treatment clonal selection and re-sensitization after drug withdrawal." (PMID 41214389, 2025). "Since EGFR phosphorylation is associated with tumor progression, we used Tyr1068/1092 and Tyr1173/1197 as reference sites." (PMID 40365309, 2025). "Statistical analysis evaluated miRNA expression across clinicopathological features, including age, gender, smoking status, tumor stage, cancer type, and EGFR mutation status." (PMID 41007624, 2025). "In many cancers, including PCa, oncogenic mutations, amplification, and overexpression of EGFR are common, contributing to tumor development, progression, and metastasis." (PMID 40808640, 2025). "Significantly upregulated eRNAs were identified near key oncogenes, including CLDN1, TP63, and EGFR, confirming transcriptional activation at these tumor-associated SEs." (PMID 41323280, 2025). "This mutation results in the deletion of exons 2–7, producing a constitutively active EGFR variant that promotes tumor growth and survival." (PMID 40563429, 2025). "Conversely, low-risk patients had better tumor immunity and were more suitable to receive EGFR- or HER2-based targeted therapy." (PMID 40777025, 2025). "This suggests that EGFR mutations can influence the microscopic morphology and texture of tumor cells, which are imperceptible to the naked eye." (PMID 40969259, 2025). "EGFR mutations are involved in tumorigenesis, tumor progression in CRC and the development of resistance to various treatments." (PMID 39722096, 2024). "This probably results from EGFR-mutant cancers’ tendency to foster an immunosuppressive tumor microenvironment, a potential cause of the diminished immunotherapy response." (PMID 39062533, 2024). "EGFR overexpression or mutation increases tumor motility, invasiveness and resistance to chemo and radiation therapies." (PMID 38557672, 2024). "To examine the clinical significance of our findings, we also performed triple‐immunostaining of CD34, α‐SMA, and YY1 on tumor sections derived from our EGFR mutated NSCLC patient cohort." (PMID 39435643, 2024). "Multivariate logistic regression was fitted to analyze the relationship between age, tumor characteristics, and EGFR mutation rates." (PMID 39722087, 2024).